GIP (gastric inhibitory polypeptide)
Diseases named in the same sentence as GIP in open-access papers (continued):
Sharing a sentence is not in itself a finding about the gene and the disease.
acromegaly (6 papers, 2019 to 2026). Acromegaly is an acquired disorder related to excessive production of growth hormone (GH) and characterized by progressive somatic disfigurement (mainly involving the face and extremities) and systemic manifestations. "Due to this expression, GIP-secretion has been linked to paradoxical increases in GH during an OGTT in approximately 30% of patients with acromegaly." (PMID 40024571, 2025). "It should be noted that results obtained in a recent study about acromegaly, shows a stimulatory effect of GIP, which is also in opposition to what was found in the present study, where a reduced level of GH was seen during high levels of GIP." (PMID 41524818, 2026). "The fasting GIP levels and its AUC before surgery were significantly higher in patients of acromegaly as compared to healthy subjects." (PMID 30948746, 2019). "IHC positivity for GIP was lower in the duodenal and colonic biopsies in patients of acromegaly, possible because of higher K-cell turnover." (PMID 30948746, 2019). "The present study is the first to document GIP levels in patients of acromegaly with different glycaemic status, both before and after surgery." (PMID 30948746, 2019). "Ratio of AUC for C-peptide/GIP was significantly higher in patients with acromegaly as compared to healthy controls." (PMID 30948746, 2019). "In support of this hypothesis, high circulating GIP levels in acromegaly may be due to increased IGF-1 levels, which induce GIP synthesis in the intestinal neuroendocrine cell line STC-1." (PMID 37344722, 2024). "The elevated GIP levels observed in patients of acromegaly in our study could have also contributed to hyperglucagonemia seen in these patients." (PMID 30948746, 2019). "Higher GIP levels in patients of acromegaly could have possibly resulted from the direct cytotrophic effect of elevated GH/IGF-1 on K-cells." (PMID 30948746, 2019). "However, when the data of all the patients of acromegaly were pooled together, there was a rank order correlation between GIP and glucagon levels (r 0.73, p < 0.001)." (PMID 30948746, 2019). "Failure of the GLP-1 levels to rise in patients of acromegaly, akin to GIP levels, can possibly be explained by the fact that GLP-1 is known to inhibit glucagon secretion and vice versa high levels of glucagon, seen in patients of acromegaly in our study, could have inhibited GLP-1 secretion." (PMID 30948746, 2019). "The pattern of expression of GIP and GLP-1 in the duodenal and colonic biopsies of patients with acromegaly has not been studied previously." (PMID 30948746, 2019). "While there are only a couple of studies investigating glucose-dependent insulinotropic polypeptide (GIP) and glucagon levels in acromegaly, there are no studies documenting the alterations in glucagon like peptide-1 (GLP-1) levels in patients with acromegaly." (PMID 30948746, 2019).
Anorexia (6 papers, 2019 to 2025). Lack of desire to eat (loss of appetite). "Although semaglutide treatment alone induced anorexia and body weight loss, GIP-085 cotreatment partially reduced hypophagia, and consequently, this resulted in a marginal yet significant attenuation of the body weight lowering effect of semaglutide treatment at 24 and 48 hours." (PMID 40532005, 2025). "However, GIP-085 enhanced semaglutide-induced anorexia, leading to a greater body weight loss compared to semaglutide alone." (PMID 40532005, 2025). "The results highlight decreased food intake and elevated PYY336 and GIP concentrations, indicating that these play a role in T-2- and HT-2-induced anorexia." (PMID 37624238, 2023). "In fact, a synergic effect between IL-1 and CCK inducing anorexia has been described, while IL-1 and GIP are factors that stimulate insulin release by the pancreas." (PMID 31191339, 2019). "T-2 toxin-triggered GLP-1 and GIP release has been observed in T-2 toxin-induced anorexia as well." (PMID 35737050, 2022). "However, when coadministered with GLP-140, GIP-085 was able to reduce kaolin consumption driven by GLP-1R activation and it also significantly attenuated GLP-140–induced anorexia at 72 hours, resulting in a 7- ± 6-g significant attenuation of GLP-140–induced body weight loss." (PMID 40532005, 2025). "GIP correlates negatively with anorexia and does not induce nausea." (PMID 34055657, 2021). "In addition, bloating correlated with CgA (r = 0.85, P = 0.03), anorexia correlated with each of secretin (r = −0.91, P = 0.01) and GIP (r = −0.95, P=0.003), and nausea correlated with each of CCK (r= –0.89, P=0.01) and GIP (r= –0.95, P=0.003) in the idiopathic IBS subgroup." (PMID 34055657, 2021).
Anxiety (6 papers, 2017 to 2023). Intense feelings of nervousness, tension, or panic often arise in response to interpersonal stresses. "Open-field test: We explored the effects of 6-OHDA lesions and GIP treatment on general locomotor activity and anxiety-related behaviors in open field tests." (PMID 29641447, 2018). "In the present study, in a unilateral 6-OHDA MFB lesion rat model of PD, we demonstrated that GIP treatment stabilized apomorphine-induced rotational behavior and showed positive changes in open field locomotor tests, as well as some anxiety-like behaviors." (PMID 29641447, 2018). "The neuroprotective effects of GIP were evaluated by apomorphine-induced contralateral rotations, as well as by locomotor and anxiety-like behaviors in open-field tests." (PMID 29641447, 2018). "One subject was dropped before both Xen infusions due to change in medication and one was dropped after both GIP plus Xen visits due to anxiety." (PMID 29466430, 2018). "Furthermore, there was also an effect of GIP treatment on anxiety-like behavior (total distance moved, velocity, freezing time, and number entries into the central zone: p = 0.031, 0.021, 0.034, and 0.008) in 6-OHDA rats except for retention times in the central zone (p = 0.218)." (PMID 29641447, 2018). "In addition, locomotor and anxiety-like behavioral changes were also ameliorated by GIP." (PMID 29641447, 2018).
Hypertension (6 papers, 2013 to 2024). The presence of chronic increased pressure in the systemic arterial system. "Infections (13% vs 6%) thromboembolism (4% vs 1%), hypertension (12% vs < 1%), GIP or fistula/abscess (15% vs 4%) and proteinuria (8% vs 0%) were the main AEs of severe grade (≥3) for the BV arm versus chemotherapy arm." (PMID 27852039, 2017). "In the GOG218 trial patients treated with the dose of 15 mg/kg of BV experienced a worse toxicity profile than patients treated with 7.5 mg/kg of BV in ICON7 trial: hypertension ≥ 2 (p = 0.003), GIP ≥ 2 (p = 0.028), proteinuria ≥ 3 (p = 0.017)." (PMID 27852039, 2017). "Serum PAI-1 and GIP levels were increased in the hypertension disorders group as compared with the HP group." (PMID 28348564, 2017). "In newly diagnosed OC, BV was linked to higher risk for events such as bleeding (RR = 3.63; p = 0.000), ATE (RR = 2.29; p = 0.003), hypertension of grade ≥ 2 (RR = 4.90; p = 0.000), GIP (RR = 2.90; p = 0.003), and with proteinuria grade ≥3 (RR = 6.63; p = 0.000)." (PMID 27852039, 2017). "However, anti-VEGF monotherapy has limited clinical benefits for cancer patients and in high dosage can often lead to various adverse effects such as hypertension, proteinuria, thromboses, and GIP." (PMID 23874680, 2013). "The most frequent diagnosis was GIP (n = 2486, 37.8%) among patients without hypertension." (PMID 36550459, 2022). "Compared to the diagnosis GIP, the patients with stage II, stage III, or stage IV periodontitis had an independent odds ratio (OR) of 1.92 (95% confidence interval [CI] 1.13–3.29; p = 0.017), 1.78 (95% CI 1.03–3.09; p = 0.039) and 2.63 (95% CI 1.48–4.68; < 0.001) for hypertension, respectively." (PMID 36550459, 2022).
periodontitis (6 papers, 2019 to 2026). An acute or chronic inflammatory process that affects the tissues that surround and support the teeth. "A previous study reported that GIPRKO mice exhibited increased inflammatory cell infiltration and elevated inflammatory gene expression in the gingiva tissue during periodontitis, suggesting a potential anti-inflammatory role of GIP in periodontal tissues." (PMID 41596254, 2026). "In severely obese populations, periodontitis correlates with elevated glucagon and GIP levels alongside reduced GLP-1, suggesting a mechanistic pathway that exacerbates glucose dysregulation." (PMID 41307071, 2025). "We previously demonstrated the beneficial effects of glucose-dependent insulinotropic polypeptide (GIP) on periodontitis via its anti-inflammatory effects using ligature-induced experimental periodontitis model mice." (PMID 33274238, 2020). "We previously demonstrated that the induction of periodontitis in GIP receptor knockout mice was more severe than that in wild-type mice and was accompanied with aggregated macrophages in the gingiva, which demonstrates the beneficial effects of GIP on periodontitis." (PMID 33274238, 2020).
medullary thyroid cancer (5 papers, 2017 to 2025). "Moreover, in genetically predisposed populations, such as those with a family history of medullary thyroid carcinoma or multiple endocrine neoplasia type 2, tirzepatide might further elevate thyroid cancer risk through GIP-mediated pathways." (PMID 41310711, 2025). "The implications of the GIP/GIP receptor axis stimulation on the occurrence of medullary thyroid cancer and patients’ prognosis remains to be elucidated." (PMID 39141075, 2024). "Finally, the use of injectable GLP-1R agonist or GIP/GLP-1R–based medications is contraindicated in patients with a personal or family history of medullary thyroid carcinoma or patients with type 2 multiple endocrine neoplasia syndrome." (PMID 40568728, 2025). "While preclinical studies suggest that GIP can induce cAMP elevation in medullary thyroid cancer cells and proliferation in colorectal cancer cells, no known in vitro or in vivo studies have examined the role of GIP signaling in breast cancer to date." (PMID 37250804, 2023).
metabolic dysfunction-associated steatotic liver disease (5 papers, 2024 to 2025). Metabolic dysfunction-associated steatotic liver disease (MASLD, formerly known as nonalcoholic fatty liver disease or NAFLD) is a type of liver disease that is not caused by alcohol. "Retatrutide, a polyagonist, targets GLP-1, GIP, and glucagon receptors, showing additional metabolic benefits and body weight reduction in individuals with metabolic dysfunction-associated steatotic liver disease (MASLD)." (PMID 40868582, 2025).
neuroendocrine tumors (5 papers, 2018 to 2025). "GIPR, which is highly expressed in group 1 tumors, encodes the receptor of glucose-dependent insulinotropic polypeptide (GIP) that has a well-known role in neuroendocrine tumors." (PMID 36497102, 2022). "This was confirmed by two distinct proof-of-principle studies using xenograft neuroendocrine tumor mouse models and two different GIP-based radioactive tracers." (PMID 32498358, 2020). "Indeed, GIPRs are found on many neuroendocrine tumors, offering the possibility of exploitation for tumor imaging, diagnosis and treatment using radioligand of GIP, PET analysis and GIPR antagonists." (PMID 40024571, 2025). "This contrasts with the literature on GPCR overexpression in other tumors, such as neuroendocrine neoplasms, where overexpression of somatostatin receptors and the receptor for gastric inhibitory polypeptide may be variable or reduced in G3 tumors in contrast to G1 and G2 tumors." (PMID 35327338, 2022). "The contribution of the GIP/GIPR axis can be further investigated in endocrine tumors, such as in functional neuroendocrine tumors, that synthesize, store and secrete peptide hormones in a cAMP-dependent manner, as findings could have potential diagnostic and therapeutic implications." (PMID 32498358, 2020).
osteoporosis (5 papers, 2017 to 2024). A condition of reduced bone mass, with decreased cortical thickness and a decrease in the number and size of the trabeculae of cancellous bone (but normal chemical composition), resulting in increased fracture incidence. "Furthermore, since osteoporosis itself is a disturbance of bone remodeling, GIP may be a novel treatment for osteoporosis." (PMID 36012183, 2022). "The aim of this review is to summarize the current knowledge of the actions of GIP, GLP-1, GLP-2, and PYY on bone metabolism, and to discuss future therapies targeting these receptors for the treatment of osteoporosis." (PMID 30863364, 2019).
breast carcinoma (4 papers, 2019 to 2025). "In this prospective case-control study nested within the Mano a Mano Cohort Study, we assessed the risk of breast cancer with regard to plasma levels of c-peptide, gastric inhibitory polypeptide, insulin, leptin, monocyte chemoattractant protein-1, pancreatic polypeptide, and peptide YY." (PMID 31292496, 2019). "Despite this, when we calculated the raw odds ratio, we found that C-peptide, GIP, GLP-1, and PAI-1 are indicators for breast cancer risk." (PMID 38397883, 2024). "A poorly studied issue in women with breast cancer is the role of incretins (GIP (glucose-dependent insulinotropic polypeptide) and GLP-1 (glucagon-like peptide-1)) in the quantity and quality of muscle mass in lean and obese individuals." (PMID 38397883, 2024). "Specifically, there is an inadequate response to GIP and GLP-1 after meals, exhibiting a biochemical pattern similar to that observed in obese women with breast cancer." (PMID 38397883, 2024). "Along with the detrimental effects on muscle function, we observed a rise in gastrointestinal incretins (GIP and GLP-1), C-peptide, and glucagon levels, along with low PAI-1 levels, in breast cancer patients, independently." (PMID 38397883, 2024). "When scaled to a 1 unit lowering of ln-fasting GIP concentrations mediated by this variant this represents ORs (95% CIs) of 1.80 (1.48–2.19), 1.94 (1.50–2.52), and 2.17 (1.33–3.54) for overall, luminal A-like, and luminal B HER2 negative-like breast cancer, respectively." (PMID 37250804, 2023).
Cushing syndrome (4 papers, 2019 to 2025). Cushing's syndrome (CS) encompasses a group of hormonal disorders caused by prolonged and high exposure levels to glucocorticoids that can be of either endogenous (adrenal cortex production) or exogenous (iatrogenic) origin. "In GIP-dependent primary bilateral macronodular adrenal hyperplasia with Cushing’s syndrome, KDMIA mutations were found to be responsible for ectopic GIPR expression but could also result in increased expression of LHCGR." (PMID 36926028, 2023). "In this form of Cushing’s syndrome, food ingestion induces GIP release from the small intestine, which binds to its receptor in the adrenal gland and causes excess cortisol secretion." (PMID 40872711, 2025). "ACTH-independent Cushing's syndrome is due to the development of ectopic GIPR expression in the adrenal cortex, which arises secondary to germline or somatic loss of KDM1A expression and gives rise to the secretion of cortisol upon release of GIP from the gut." (PMID 40024571, 2025).
insulinoma (4 papers, 2017 to 2025). "Disturbances relating to GIP are also encountered in cases of insulinoma, including the production of GIP and expression of GIP receptors." (PMID 40024571, 2025). "Suppression of GATA-4 in GIP-producing GTC-1 cells, a subclone of STC-1 cells, decreases GIP promoter activity, while its overexpression in mouse insulinoma βTC-3 cells increases expression and secretion of GIP." (PMID 40024571, 2025). "Human insulinomas generally exhibit markedly disturbed stimulus-secretion coupling pathways, explaining why the insulinotropic effect of GIP is almost abolished in many insulinoma patients." (PMID 40024571, 2025). "High-affinity binding of radiolabeled GIP has been shown in rat insulinoma RINm5F cells, hamster pancreatic β-cells, and membrane preparations of hamster β-cell tumors." (PMID 40024571, 2025). "Studies in hamster insulinoma HIT T15 cells transfected with human GIP reporter genes show that transcription may be induced by increased level of cAMP, and that the ∽180 bp region prior to the transcription start of the GIP gene is sufficient for basal GIP transcription." (PMID 40024571, 2025).
Stroke (4 papers, 2017 to 2025). Sudden impairment of blood flow to a part of the brain due to occlusion or rupture of an artery to the brain. "Future large-scale RCTs are needed to elucidate the effects of GIP/GLP-1RA on primary and secondary stroke prevention." (PMID 39407846, 2024).
amyloid (3 papers, 2019 to 2025). "Meanwhile, GIP analogues have been reported to protect against the amyloid-induced impairment of synaptic plasticity in the hippocampus." (PMID 35204073, 2022). "GIP injection ip., had protective effects on spatial learning in memory tasks and also reduced plaque formation and amyloid load in a different AD mouse model." (PMID 31068799, 2019).
cardiac hypertrophy (3 papers, 2020 to 2025). "Decreased Ang II-mediated expression of Tgf-β1 is also observed after GIP treatment in ApoE KO mice, and this is paralleled by decreased expression of hypoxia inducible factor-1α (Hif-1α), a proinflammatory transcription factor that promotes cardiac hypertrophy in mice." (PMID 40024571, 2025). "GIP further decreases cardiac hypertrophy and interstitial fibrosis in diabetic db/db mice and decreases NADPH oxidase-driven superoxide production and expression of markers indicative of fibrosis (Ctgf) and heart hypertrophy (β-Mhc and Tgf-β2) in isolated mouse cardiomyocytes." (PMID 40024571, 2025).
chronic pancreatitis (3 papers, 2015 to 2025). A chronic inflammatory process causing damage and fibrosis of the pancreatic parenchyma. "Impaired GIP-induced insulin secretion is further observed in the setting of chronic pancreatitis, and in individuals with mutations in HNF1α (MODY3 diabetes)." (PMID 40024571, 2025). "Postprandial GIP secretion is impaired in chronic pancreatitis and cystic fibrosis-related diabetes (CFRD), and as might be expected improved following pancreatic enzyme substitution." (PMID 40024571, 2025). "In a pilot study involving eight males with chronic pancreatitis treated with PERT and eight matched healthy controls, the authors found a direct relationship between nutrient assimilation and postprandial levels of GLP-1 and GIP." (PMID 38398492, 2024).
colitis (3 papers, 2021 to 2025). Inflammation of the colon. "Elevated plasma GIP levels, impaired enteric neuronal function, and diminished colonic smooth muscle responses have been observed in animal models of colitis." (PMID 40723884, 2025). "In conclusion, we evaluated the prebiotic effects of G. lucidum and G. incarnatum’s different consumption ways (GLP, GLE, GIP, and GIE) on DSS-induced colitis." (PMID 36553765, 2022). "However, the expression profiles of GIP and GIP-R in the small intestine of healthy individuals, patients with IBD, and animal models of colitis remain incompletely characterized." (PMID 40723884, 2025). "In contrast, GLP, GIP, and GIE did not have a positive effect on relieving colitis." (PMID 36553765, 2022).
depression (3 papers, 2017 to 2023). "Similarly, UBE2Z, GIP and IGF2BP1 have been linked to CAD, T2D, and depression-related traits such as insomnia, BMI, educational attainment, CRP levels, platelet count and smoking." (PMID 37390107, 2023).
inflammatory bone diseases (3 papers, 2024 to 2026). "In this study, we revealed the inhibitory effect of (D-Ala2)GIP on TNF-α-induced osteoclast formation and bone resorption in vivo, highlighting the potential of targeting GIP signaling as a therapeutic strategy for TNF-α-associated inflammatory bone diseases." (PMID 41516077, 2025). "(D-Ala2)GIP might also ameliorate bone destruction in chronic inflammation if applied long term, supporting advancements in therapies for inflammatory bone diseases." (PMID 38473802, 2024). "Moreover, no studies to date have explored GIP signaling in other inflammatory bone diseases, such as osteomyelitis." (PMID 41596254, 2026).